CLEC20A (C-type lectin domain containing 20A)
Synonyms: FLJ44005; RP4-593C16.2; LINC00083; NCRNA00083
Tractability: Antibody: UniProt predicts a signal peptide or a membrane-spanning region.
Gene: Protein-coding gene on chromosome 1 (178,479,240 to 178,499,634, reverse strand). Ensembl gene ENSG00000188585.
Homologues: Orthologues: chimpanzee CLEC20A (99% identical), macaque CLEC20A (92% identical), dog CLEC20A (60% identical), rat Clec20a (49% identical).